ROR1 (ROR family WNT receptor 1)
Diseases named in the same sentence as ROR1 in open-access papers (continued):
Sharing a sentence is not in itself a finding about the gene and the disease.
lung adenocarcinoma (26 papers, 2013 to 2025). A carcinoma that arises from the lung and is characterized by the presence of malignant glandular epithelial cells. "Our findings reveal a novel function of Rif in mediating Wnt5a-Ror1-Dvl2 signaling, which is associated with the formation of polarized filopodia on 3D matrices in lung adenocarcinoma cells." (PMID 37703992, 2023). "Here, we uncovered a novel function of Rif in mediating Wnt5a-Ror1-Dvl2 signaling, which is associated with the formation of polarized filopodia on 3D matrices in lung adenocarcinoma (LUAD) cells." (PMID 37703992, 2023). "42% of lung adenocarcinoma patients express ROR1, with 38% exhibiting high levels of expression, making ROR1 a viable target for the treatment of NSCLC." (PMID 39849645, 2025). "Given ROR1’s onco-embryonic expression, targeting its scaffold function presents a promising strategy for improving treatment outcomes in lung adenocarcinoma." (PMID 39769452, 2024). "In lung adenocarcinoma, ROR1 acts as a scaffold for cavin-1 and caveolin-1 (CAV1), two proteins critical for caveolae formation and function." (PMID 39769452, 2024). "Lung adenocarcinoma cells cultured on Matrigel established front–rear polarity with massive filopodia on their front surfaces, where Ror1 and Rif were accumulated." (PMID 37703992, 2023). "Our immunohistochemical analysis revealed a high frequency of coexpression of Ror1 and Rif in lung adenocarcinoma." (PMID 37703992, 2023). "The silencing of ROR1 significantly inhibited the proliferation of tumor cells in lung adenocarcinoma via the PI3K/AKT/mTOR signaling pathway." (PMID 37111634, 2023). "The group led by Dr. Takashi Takahashi investigated the role of ROR1 in lung adenocarcinoma in a series of studies and found that ROR1 supported pro-survival signaling in both kinase-dependent and kinase-independent manner." (PMID 34123850, 2021). "In the present study, we examined the mRNA expression of ROR1 in 56 lung adenocarcinoma patients by qRT-PCR." (PMID 33172431, 2020). "Among the 56 lung adenocarcinoma samples, qRT-PCR showed ROR1 overexpression in 16 cases (28.6%) considering a cut-off value r = 1, while accounting for the median, patients with ROR1 overexpression were 29 (51.8%)." (PMID 33172431, 2020). "Our previous investigation of patients with lung adenocarcinoma revealed that >60% of tumor tissues expressed ROR1, and inhibition of ROR1 significantly downregulated the proliferation of NSCLC cells and induced cell apoptosis." (PMID 31452776, 2019). "Our previous data suggested that the AKT/mTOR signaling pathway is necessary for ROR1-mediated proliferation and antiapoptosis in lung adenocarcinoma." (PMID 31452776, 2019). "In conclusion, the present study identified that ROR1 is a potential target for preventing erlotinib resistance in lung adenocarcinomas via the AKT/mTOR signaling pathway." (PMID 31452776, 2019). "Further studies should investigate the functions of ROR1 in lung adenocarcinoma to promote the development of ROR1-targeting therapies in the future." (PMID 31452776, 2019). "The current results demonstrated that ROR1 inhibition plus erlotinib have additional cytotoxic effect in ROR1 positive lung adenocarcinoma cell lines." (PMID 31452776, 2019). "In summary, the present study provided a novel therapeutic strategy to increase the sensitivity of ROR1+ lung adenocarcinoma to erlotinib treatment." (PMID 31452776, 2019). "Activated ROR1 has been shown to trigger AKT in lung adenocarcinoma cells and ROR1 knockdown induced dephosphorylation of AKT and apoptosis." (PMID 29856777, 2018). "Considering its onco-embryonic expression, inhibition of the scaffold function of ROR1 in patients with lung adenocarcinoma is an attractive approach for improved treatment of this devastating cancer." (PMID 26725982, 2016). "The receptor tyrosine kinase-like orphan receptor 1 (ROR1) sustains prosurvival signalling directly downstream of the lineage-survival oncogene NKX2-1/TTF-1 in lung adenocarcinoma." (PMID 26725982, 2016).
lung adenocarcinoma (continued). "In the following study it is more interesting to study the relationship between ROR1 expression and EGFR mutation status in larger population of lung adenocarcinoma patients." (PMID 25978653, 2015). "The finding of ROR1-mediated proliferation signals in both tyrosine kinase inhibitor (TKI)-sensitive and -resistant tumor cells provides encouragement to develop ROR1-directed targeted therapy in lung adenocarcinoma, especially those with TKI resistance." (PMID 25978653, 2015). "In contrast no or low expression of ROR1 was found in human squamous lung cancer (unpublished data) which indicates that ROR1 expression is more correlated with lung adenocarcinoma." (PMID 25978653, 2015). "In order to assess the suitability of ROR1 as a cell surface antigen for targeted therapy of lung adenocarcinoma, we carried out a comprehensive analysis of ROR1 protein expression in human lung adenocarcinoma tissues and cell lines." (PMID 25978653, 2015). "In conclusion the present findings identify ROR1 as a potential oncogene target in lung adenocarcinomas." (PMID 25978653, 2015). "It will be important to clarify the relationship of MET and EGFR with ROR1 in lung adenocarcinoma patients." (PMID 25978653, 2015). "We did observe that although the proportion of weakly or focally expressed ROR1 was much higher in stage I and II lung adenocarcinoma patients, moderately expressed ROR1 was more frequently found in stage III and IV patients." (PMID 25978653, 2015). "It is of particular interest that ROR1 inhibition appears to be effective for treatment of TKI-resistant lung adenocarcinomas with various resistance mechanisms." (PMID 25978653, 2015). "Functionally, TTF-1 induced ROR-1 is necessary to sustain the EGFR signaling pathway in lung adenocarcinoma cell lines." (PMID 23922984, 2013). "ROR1 was broadly expressed on many tumor cells, including lung adenocarcinomas cell A54930,31." (PMID 35484298, 2022). "Silencing of ROR1 led to growth inhibition in cell lines representing human lung adenocarcinoma." (PMID 34123850, 2021). "In lung adenocarcinoma, ROR1 functions as an independent prognostic predictor for OS." (PMID 33445713, 2021). "This study aimed to assess the expression of ROR1 in lung adenocarcinoma (AC) patients." (PMID 33172431, 2020). "Moreover, a recent study reports that ROR1 enhances lung adenocarcinoma growth by activating the Akt/GSK-3α/β/mTOR signaling cascade." (PMID 33172431, 2020). "However, kinase activity was attributed to ROR1 upon observation that the survival of lung adenocarcinoma cells was maintained through phosphorylation of c-SRC by ROR1 and activation of AKT in these cells." (PMID 30832318, 2019). "ROR1 is also required to sustain the association between EGFR and receptor tyrosine-protein kinase erbB-3 (ERBB3), the activation of ERBB3, consequentially, making ROR1 an ideal target for therapies against EGFR-TKI resistance in lung adenocarcinoma." (PMID 31452776, 2019). "Moreover, ROR1 appears to possess a distinctive attractiveness as a molecular target for the treatment of NSCLCs, especially lung adenocarcinoma." (PMID 26725982, 2016). "In tissues of lung adenocarcinoma patients we found that totally 65% (24/37) of human lung adenocarcinoma expressed ROR1, including 38% (14/37) with weak or focal expression (Score 1), 16% (6/37) with moderate expression (Score 2), and 11% (4/37) with strong expression (Score 3)." (PMID 25978653, 2015). "We also examined how ROR1 mediates survival signals in lung adenocarcinomas." (PMID 25978653, 2015). "We found about 65% of human lung adenocarcinoma tissues studied express ROR1." (PMID 25978653, 2015). "To examine expression of ROR1 in lung adenocarcinoma, we first chose Erlotinib-sensitive cell line PC-9, Erlotinib-partially sensitive cell line NCI-H358, and Erlotinib-resistant cell lines XLA-07, A549, NCI-H1975, and MSTO-211H, to determine ROR1 expression by flow cytometry." (PMID 25978653, 2015).
lung adenocarcinoma (continued). "Additionally, among lung adenocarcinoma patients with stage I and II (n = 29), 41% (12/29) had weak or focal expression, 14% (4/29) had moderate expression, and 14% (4/29) had strong ROR1 expression." (PMID 25978653, 2015). "Although ROR1 expression in lung adenocarcinoma has been shown, the association of ROR1 expression with disease stages has not previously been studied extensively." (PMID 25978653, 2015). "Based on our results we speculate that the PI3K/AKT/mTOR signaling pathway could be one of the ways that ROR1-mediated survival signaling occurs in lung adenocarcinoma." (PMID 25978653, 2015). "Our data show that ROR1 protein is selectively expressed on lung adenocarcinoma cells, but do not support the hypothesis that expression levels of ROR1 are associated with aggressive disease." (PMID 25978653, 2015). "ROR1 was also found as a scaffold protein of cavin-1 and caveolin-1, which activated AKT in lung adenocarcinoma." (PMID 34123850, 2021). "ROR1 has been suggested to be a survival factor for various malignancies including chronic lymphocytic leukemia (CLL), breast cancer, lung adenocarcinoma, ovarian carcinoma, pancreatic carcinoma and glioblastoma." (PMID 29856777, 2018). "When we examined PI3K/AKT/mTOR signaling pathways to explain ROR1-mediated survival signals in lung adenocarcinomas, we found that silencing of ROR1 significantly decreased phosphorylation of both AKT and mTOR in ROR1+ PC-9 and NCI-H1975 cells." (PMID 25978653, 2015). "Lung adenocarcinoma cells also express elevated levels of ROR1 when compared to adjacent non-tumor tissue cells." (PMID 36873868, 2023). "A study found that ROR1 expression was increased in lung adenocarcinoma in comparison to noncancerous lung tissue and that high ROR1 expression was associated with poor patient prognosis." (PMID 38213538, 2023). "In lung adenocarcinoma cell lines NCI-H1975 and SK-LC-5, NKX2-1, a homeodomain transcription factor, has been shown to directly induce the expression of ROR1, which in turn sustains a favorable balance between prosurvival PI3K-AKT and pro-apoptotic p38 signaling." (PMID 28427197, 2017). "Furthermore, ROR1, a constituent gene of Wnt signaling pathway, plays a sustainer role in EGFR-mediated prosurvival signaling in lung adenocarcinoma via signaling cross-talk and was therefore reported to be a potential therapeutic target." (PMID 25599599, 2015). "We found ROR1 protein expressed in lung adenocarcinoma but almost absent in tumor-adjacent tissues of the patients." (PMID 25978653, 2015). "In lung adenocarcinoma, NKX2-1 (TITF1) has been shown to drive ROR1 expression and the subsequent increase in ROR1 has two distinct proposed functions, including the potentiation of EGF ligand-induced EGFR signaling and the phosphorylation and activation of c-Src regardless of ligand induction." (PMID 24752542, 2014). "Overall, the data indicate a role of ROR1 expression in lung adenocarcinoma, which may be independent of ROR1 kinase activity." (PMID 37111634, 2023). "In order to clarify the growth-enhancing role of ROR1 in lung adenocarcinoma, we choose the TKI-resistant NCI-H1975 and XLA-07 cell lines and TKI-sensitive PC-9 cell line and found that blocking of ROR1 could significantly induce apoptosis and growth-inhibition of all those cell lines." (PMID 25978653, 2015). "However, it was not known whether ROR1 expression in patients with lung adenocarcinoma had functional and clinical significance." (PMID 25978653, 2015). "Possible reasons include: too few numbers of patients especially those with stages III and IV as well as those with scores 2 and 3 and the possibility that the phosphorylation and glycosylation level, but not the expression level of ROR1 may be correlated with aggressive lung adenocarcinoma." (PMID 25978653, 2015).
lung adenocarcinoma (continued). "In the following experiment, we chose MSTO-211H as ROR1 negative cell line, PC-9, XLA-07, and NCI-H1975 as ROR1 positive cell lines to determine the role of ROR1 in lung adenocarcinoma." (PMID 25978653, 2015).
triple-negative breast carcinoma (26 papers, 2019 to 2025). An invasive breast carcinoma which is negative for expression of estrogen receptor (ER), progesterone receptor (PR), and human epidermal growth factor receptor 2 (HER2). "A trial of PRGN-3007 UltraCAR-T cells (NCT05694364) targeting ROR1 is currently under clinical development for patients with hematologic malignancies as well as ROR1+ triple negative breast cancers." (PMID 39835140, 2024). "Another phase I trial of autologous T cell therapy for patients with ROR1+ triple negative breast cancer and ROR1+ non-small cell lung cancer (NCT02706392) assessed the safety profile in six patients, and no DLT was observed." (PMID 39835140, 2024). "Strictinin, isolated from Myrothamnus flabellifolius, targeted the intracellular region of ROR1 and induced apoptosis of triple-negative breast cancer cells (TNBC) through the intrinsic apoptotic pathway." (PMID 37111634, 2023). "We have developed a next-generation armored CAR (F i-CAR) targeting receptor tyrosine kinase-like orphan receptor 1 (ROR1), which is expressed at high levels in a range of aggressive tumors including poorly prognostic triple-negative breast cancer (TNBC)." (PMID 35659040, 2022). "As such, it was demonstrated that exposure to TGFβ impairs proliferation as well as cytokine production of receptor tyrosine kinase-like orphan receptor 1 (ROR1)-specific CAR T cells co-cultured with ROR1-expressing triple-negative breast cancer cells." (PMID 33546277, 2021). "MiR-30a can inhibit EMT and metastasis of triple-negative breast cancer cells by targeting ROR1." (PMID 35111745, 2021). "We investigated ROR1 immunophenotype using validated antibody clones for immunohistochemistry (IHC) and flow cytometry (FC), analyzing 292 tumour specimens from 7 haematological malignancies and triple negative breast cancer (TNBC) as a reference solid tumour indication." (PMID 39495778, 2024). "Finally, to bridge a comparison of ROR1 levels between haematological and solid tumours, we included a cohort of triple negative breast cancer (TNBC) FFPE tumour tissues as a reference solid tumour type profiled with a significant fraction of ROR1+ tumour cells." (PMID 39495778, 2024). "An additional trial using Lyl797, a ROR1-targeted CAR-T cell, enrolled patients with triple-negative breast cancer or NSCLC (NCT05274451)." (PMID 39796666, 2024). "Surprisingly, the ROR1 mRNA was highly expressed in HER2+ and triple-negative breast cancer (TNBC) tumors primarily in those patients who had a progressive, stable, or partial response to treatment." (PMID 38296962, 2024). "A ROR1 targeted CAR T cell therapy, LYL797, is being tested in patients with advanced lung and triple negative breast cancers (NCT05274451)." (PMID 39835140, 2024). "LYL797 is a ROR1-targeted CAR T-cell therapy currently being investigated in patients with ROR1 who have pre-treated NSCLC and triple-negative breast cancer (NCT05274451)." (PMID 39518043, 2024). "In parallel with these pre-clinical developments, a clinical trial of ROR1-targeted CAR T-cells in patients with NSCLC and triple-negative breast cancer (TNBC) was initiated at the Fred Hutchinson Cancer Center (NCT02706392)." (PMID 36829563, 2023). "Significantly, owing to the higher expression of ROR1 in NSCLC and triple-negative breast cancer ROR1 has been employed as a target of chimeric antigen receptor (CAR) T cell therapy." (PMID 34319035, 2021). "Further, miR-30a-5p targets the ROR1, the orphan like receptor tyrosine kinase (RTK), reducing EMT and metastasis formation in triple-negative breast cancer." (PMID 33562690, 2021). "A phase I trial (NCT02706392) is currently recruiting ROR1 positive cancers such as CLL and triple negative breast carcinoma." (PMID 32807831, 2020). "One study found high ROR1 staining in 56% of triple-negative breast cancer samples and low ROR1 staining in 12% of ER+PR+ samples and no staining in 12 HER2+ samples." (PMID 38408999, 2024).
pancreatic cancer (23 papers, 2015 to 2025). "There have also been investigated that high expression of ROR1 in other solid tumors, including colorectal cancer, gastric cancer, melanoma, and pancreatic cancer, was associated with poor prognosis." (PMID 37241228, 2023). "Ours is the first study to investigate an association between ROR1 protein expression and overall survival in pancreatic cancer patients." (PMID 34763666, 2021). "and colleagues indicated that SCFA enhanced CD25 expression and the secretion of IFN-γ and TNF-α in CAR-T cells targeting tyrosine kinase-like orphan receptor 1 (ROR1), resulting in anti-tumor effects in syngeneic murine melanoma and pancreatic cancer models." (PMID 39044834, 2024). "The researchers showed that co-culture of a range of ROR1-expressing pancreatic cancer cell lines with unstimulated T-cells and ROR1 BiTE resulted in specific in vitro cytotoxicity even at very low concentrations (0.1ng/ml)." (PMID 39759138, 2024). "When tested in vivo, ROR1 BiTE prevented engraftment of pancreatic tumor xenografts in mice and reduced the size of established subcutaneous tumors by at least 3-fold." (PMID 39759138, 2024). "KMT5A upregulates the expression of stemness and EMT-related genes in pancreatic cancer cells by inducing the expression of the receptor tyrosine kinase-like orphan receptor 1 (ROR1)." (PMID 36902253, 2023). "The non-canonical pathway receptor ROR1 is overexpressed in circulating tumor cells from pancreatic cancer patients and knockdown of ROR1 reduces invasiveness (Xu, Shen, Xu, Wang, & Ni, 2018)." (PMID 35358569, 2022). "Two previous studies using independent ROR1 antibodies (4A5 and 6D4 monoclonal antibodies) have investigated ROR1 protein expression in small cohorts of pancreatic cancer tissues." (PMID 34763666, 2021). "An early study into ROR1 protein expression across a range of tumour types reported “moderate” or “high” expression in 83% of pancreatic cancer samples (n = 48) using the high-affinity 4A5 monoclonal antibody against ROR1." (PMID 34763666, 2021). "This raises the possibility of using ROR1 targeting therapies in future pancreatic cancer treatment." (PMID 34763666, 2021). "Nonetheless, a small molecule compound dubbed KAN0439834 was found to inhibit the survival of CLL and pancreatic cancer cells, as well as phosphorylation of ROR1 in cell-based assays." (PMID 34123850, 2021). "While neither study investigated an association with overall survival, the detection of ROR1 protein expression prompted interest in pursuing ROR1 therapeutics in pancreatic cancer treatment." (PMID 34763666, 2021). "On a molecular level, KAN0439834 inhibited the phosphorylation of PI3K/AKT/mTOR/CREB and SRC, both in CLL as well as in pancreatic cancer cells, and thus blocked major pro-survival pathways induced by ROR1." (PMID 33445713, 2021). "Immunohistochemistry (IHC) using the validated anti ROR1 monoclonal antibody (4A5) was performed on the Australian Pancreatic Cancer Genome Initiative (APGI) cohort of PDAC samples (n = 152)." (PMID 34763666, 2021). "There are also reports on the expression of ROR1 in other types of cancer, including colorectal cancer, endometrial cancer, gastric cancer, melanoma, and pancreatic cancer." (PMID 34123850, 2021). "In Ewing sarcoma, ROR1 expression was markedly higher in metastases than in localized disease, and in pancreatic cancer, ROR1 was identified on circulating tumor cells (CTCs) as an essential factor for their invasive phenotype." (PMID 33445713, 2021). "In this regard, HCC is similar to pancreatic cancer where almost all cell lines expressed ROR1 but with minor differences in abundance." (PMID 30832318, 2019). "KAN0439834 induced a significantly (p<0.05 ‒ <0.001) higher rate of apoptosis than the anti-ROR1 mAb in all pancreatic cancer cell lines." (PMID 29856777, 2018).